NLRP3 (NLR family pyrin domain containing 3)
Diseases named in the same sentence as NLRP3 in open-access papers (continued):
Sharing a sentence is not in itself a finding about the gene and the disease.
kidney stones (14 papers, 2021 to 2025). "Many factors promote the assembly and activation of NLRP3, as seen in nephrolithiasis and its association with CKD." (PMID 40529990, 2025). "Inhibiting CaOx crystal induced renal cell pyroptosis, including downregulating the expression of NLRP3, caspase-1, IL-1β, and other related pyroptosis proteins, can reduce the risk of kidney stone formation." (PMID 39768161, 2024). "Studies have shown that COM crystals induce NLRP3 activation and lead to pyroptosis, which is considered to be one of the causes of kidney stone formation." (PMID 39768161, 2024). "M2-macrophages associated phagocytosis could suppress kidney stone development through serval mechanisms, including NLRP3, miR-93-TLR4/IRF1, and miR-185-5p/CSF1 pathways." (PMID 36932340, 2023). "Emerging therapies targeting NLRP3 offer potential strategies to mitigate kidney stone-induced inflammation and CKD progression." (PMID 40529990, 2025). "After confirming the knockdown efficiency by measuring the mRNA and protein levels of NLRP3, we constructed an in vitro kidney stone model using Ox stimulation." (PMID 40384863, 2025). "This review explores the pivotal role of the NLRP3 inflammasome in kidney stone-related inflammation." (PMID 40529990, 2025). "Future studies should focus on optimizing NLRP3-targeted therapies, assessing their long-term effects on kidney stone prevention and CKD progression." (PMID 40529990, 2025). "To further investigate the mechanism of cellular damage during kidney stone formation, we focused on NLRP3/GSDMD-mediated pyroptosis." (PMID 40384863, 2025). "Some studies suggest that the inflammatory damage induced by NLRP3 activation and its mediated pyroptosis are the nodal points for the formation of kidney stones." (PMID 39768161, 2024). "Calcium oxalate crystals, a key component in kidney stones, induce an inflammatory response by activating the NLR family pyrin domain containing 3 inflammasome (NLRP3), resulting in the release of pro-inflammatory cytokines IL-1β and IL-18." (PMID 38281018, 2024). "Activation of the NLRP3 inflammasome leads to the initial stages and progression of many diseases, including kidney stones." (PMID 34512861, 2021). "In calcium oxalate–induced kidney stones, lncRNA‐00339 promotes renal tubular epithelial cell pyroptosis by regulating the miR‐22‐3p/NLRP3 axis." (PMID 34296520, 2021). "The LINC00339/miR‐22‐3p/NLRP3 axis in kidney stones induced by calcium oxalate promotes renal tubular epithelial pyroptosis." (PMID 33270361, 2021). "Here, we found that gasdermin D (GSDMD)-mediated pyroptosis occurred in both patients and mice with calcium oxalate (CaOx) nephrolithiasis, and the expression levels of NOD-like receptor protein 3 (NLRP3) and GSDMD were associated with the severity of kidney stones." (PMID 40384863, 2025). "Calcium oxalate crystals activate the NLRP3 inflammasome, leading to the release of pro-inflammatory factors such as IL-1β and increased production of reactive oxygen species (ROS), triggering oxidative stress and promoting the formation of kidney stones." (PMID 41019076, 2025). "By interrupting the inflammatory cycle driven by NLRP3 activation, CP-456,773 could indirectly slow nephrolithiasis progression, making it a valuable therapeutic candidate for inflammation-associated kidney stone disease." (PMID 40529990, 2025). "All these results suggest that the NLRP3/GSDMD axis is activated in the kidneys of patients and mice with renal calculi, indicating the potential involvement of pyroptosis in the pathogenesis of CaOx kidney stones." (PMID 40384863, 2025). "Quantitative analysis revealed significantly higher mRNA expression of NLRP3, GSDMD, and crystal adhesion factor (cluster of differentiation 44, CD44) in kidney stone samples than in normal samples." (PMID 40384863, 2025).
kidney stones (continued). "Furthermore, to investigate the role of NLRP3/GSDMD-mediated pyroptosis in renal stone formation, we conducted qRT-PCR assays on blood samples (20 normal individuals vs. 20 kidney stone patients)." (PMID 40384863, 2025). "Only studies show that TXNIP, NLRP3, and other genes are upregulated in the in vivo model of kidney stone mice, but they do not link ERS with pyroptosis." (PMID 39768161, 2024). "Our collective results indicate that the NLRP3/GSDMD signaling pathway is involved in the upregulation of inflammatory factors and adhesion molecule-related proteins, and the absence of GSDMD hinders renal inflammation and pyroptosis-induced cell death, thereby attenuating kidney stone formation." (PMID 40384863, 2025).
leishmaniasis (14 papers, 2012 to 2025). Infectious disease that is transmitted through the bite of hematophagous female phlebotomine sand flies. "Several studies have been conducted to increase our understanding of the underlying mechanisms of NLRP3 activation during leishmaniasis." (PMID 38623843, 2024). "There are studies showing both a protective and a pathologic effect of NLRP3 activation in mouse models of leishmaniasis." (PMID 41451223, 2025). "Still, our data demonstrated an overall increased expression of inflammasome-related genes such as Gsdmd, Nlrp3, Casp1, Casp4, Il1b, Ifng, Tnfa, Il10, and Il17a when we compared Leishmaniasis patients with controls." (PMID 36828815, 2023). "Nevertheless, the activation of the NLRP3 plays a crucial role in determining the outcome of leishmaniasis." (PMID 38097942, 2023). "Although NLRP3 is thought to be protective against leishmaniasis, there is evidence suggesting a synergistic role of this inflammasome in the pathogenesis of the parasite." (PMID 38097942, 2023). "Confirming the relevance of these findings to human leishmaniasis, blockade of the NLRP3 inflammasome in skin biopsies from leishmania-infected patients prevented IL-1β release." (PMID 28192528, 2017). "In contrast, during Leishmaniasis, Nlrp3 also promotes Th2-biased adaptive immunity in an inflammasome-dependent manner through IL-18." (PMID 27926940, 2016). "Recent advances in research have indicated crucial role for NLRP3 inflammasomes during Leishmaniasis.NLRP3 inflammasomes exert strong control over IL-1β and IL-18 production, and these cytokines are considered key mediators during Leishmania infections both in vitro and in vivo." (PMID 38623843, 2024). "In another study aiming to understand the role of the NLRP3 inflammasome in Th1/Th2 responses during leishmaniasis, knockout BALB/c mice for NLRP3, ASC, or caspase-1, displayed deficient IL-1β and IL-18 production and were resistant to cutaneous L. major infection." (PMID 38623843, 2024). "The role of NLRP3 in leishmaniasis seems to be like a double-edged sword." (PMID 38097942, 2023). "Together, these studies in animal models of leishmaniasis suggest that any component of the NLRP3 inflammasome may have a role in the pathogenesis of leishmaniasis." (PMID 37276232, 2023). "Therefore, activation of the NLRP3 inflammasome promoting resistance appeared to be species-specific in leishmaniasis." (PMID 31233552, 2019). "By employing two different murine models of infection, we found that CD8+ T cell-induced pathology depended on the NLRP3 inflammasome and IL-1β signaling, and demonstrated that the NLRP3 inflammasome is required for the high levels of IL-1β present within lesions of leishmaniasis patients." (PMID 28192528, 2017). "Active NLRP3 inflammasome and GSDMD are present in skin biopsies of patients, demonstrating activation of this pathway in human leishmaniasis." (PMID 36828815, 2023). "To assess inflammasome activation in skin biopsies of Leishmaniasis patients, we stained the patient tissues with anti-ASC, anti-NLRP3, and cleaved GSDMD (N-terminal)." (PMID 36828815, 2023). "In summary, while the knockout mice studies indicate that NLRP3 activation during leishmaniasis is important for infection control, several studies have shown that the lack of NLRP3 also leads to a reduction in infection severity and mortality." (PMID 38623843, 2024). "Using a combination of murine models and studies in cutaneous leishmaniasis patients, we have identified the NLRP3 inflammasome and IL-1β as components of the pathologic response that occurs as a consequence of CD8+ T cell cytotoxicity in severe forms of leishmaniasis." (PMID 28192528, 2017).
Sjögren’s syndrome (14 papers, 2015 to 2026). "In contrast, in Sjögren’s syndrome, NLRP3 activation within salivary gland epithelial cells promotes IL-1β–mediated acinar cell injury and contributes to xerostomia and glandular dysfunction." (PMID 41596738, 2026). "NLRP3-driven inflammation contributes to glandular epithelial injury and secretory dysfunction in salivary gland disorders such as Sjögren’s syndrome (SS)." (PMID 41596738, 2026). "In Sjögren syndrome (SS), a chronic inflammatory disorder, aberrant activation of the NLRP3 and AIM2 inflammasome pathway was confirmed." (PMID 41440367, 2025). "Thus, NLRP3, AIM2 and IFI16 are components of the innate immune system that are activated in Sjögren syndrome." (PMID 41440367, 2025). "Interestingly, the NLR Family Pyrin Domain Containing 3 (NLRP3) inflammasome is highly expressed and activated in splenic MDSCs of NOD mice with Sjögren’s Syndrome-like manifestation; thus, these cells produce increased levels of IL-1β." (PMID 38495880, 2024). "Additionally, it was suggested that activation of NLRP3 in MDSCs of NOD mice is induced by IL-27, a cytokine showing pro-inflammatory and anti-inflammatory effects with roles do not elucidated completely in Sjögren’s Syndrome." (PMID 38495880, 2024).
uveitis (14 papers, 2016 to 2025). An inflammatory process affecting a part of or the entire uvea. "Ocular involvement specifically uveitis was most commonly identified in NLRP3 low-penetrance variants (n = 12; 63%) in comparison to TNFRSF1A- (n = 14; 24%, p = 0.0169) and MEFV variants (n = 6; 18%, p = 0.0141)." (PMID 32563262, 2020). "The present study investigates the role of the NLRP3 inflammasome in the chronicity of ocular inflammation in uveitis using the experimental autoimmune uveitis (EAU) model." (PMID 40156826, 2025). "In the presence of a pathogenic or likely pathogenic NLRP3 genetic variant, only one of the following symptoms are needed for NLRP3-AID classification: urticarial rash, red eye (conjunctivitis, episcleritis, uveitis) or neurosensorial hearing loss." (PMID 39618694, 2024). "miR‐223‐3p can negatively regulate the Nod‐like receptor family pyrin domain‐containing protein 3 (NLRP3), affecting the progression of uveitis." (PMID 39611043, 2024). "Currently, a large number of experiments both domestically and internationally have shown that the NLRP3 inflammasome plays an important regulatory role in the pathogenesis of uveitis." (PMID 39611043, 2024). "In peripheral blood mononuclear cell samples of patients with Behçet’s disease, which is one of the uveitis-related chronic inflammatory diseases, NLRP3 expression level is upregulated during the onset of disease." (PMID 35836195, 2022). "These surprising findings cast doubt on the role of NLRP3 inflammasome in the pathogenesis of uveitis, raising the question of whether it is necessary or dispensable for the development of uveitis." (PMID 35836195, 2022). "Phenotypes of uveitis and central nervous system involvement were lacking, whereas these two organ involvements were unique features of NLRP3-AID, especially MWS." (PMID 34249981, 2021). "In our cohort of adult NLRP3-AID, we have reported that only 29% of patients had occasional oral aphthous ulcers, but no genital or perianal ulcers, folliculitis, or uveitis." (PMID 34249981, 2021).
viral myocarditis (14 papers, 2018 to 2025). Myocarditis that is caused by an infection with a viral agent. "More and more evidence indicate NLRP3 inflammasome activation is associated with the development of various inflammatory diseases including viral myocarditis." (PMID 38643118, 2024). "In this study, our findings indicate activated pyroptosis in viral myocarditis and we have confirmed that IL-37 significantly inhibits the activation of NLRP3 inflammasome caused by CVB3." (PMID 36418383, 2022). "Colchicine prevents disease progression in viral myocarditis via modulating the NLRP3 inflammasome in the cardiosplenic axis." (PMID 39912853, 2025). "For instance, miR-15 has been found to upregulate the levels of NLRP3 and caspase-1 p20, thereby promoting the activation of NLRP3 inflammasome and aggravating the inflammatory response of viral myocarditis." (PMID 38643118, 2024). "Meanwhile, NLRs and RAGEs both play roles in the viral myocarditis through the NLRP3 inflammasome and RAGE/Dia pathways, respectively." (PMID 36827455, 2023). "Colchicine can reduce the expression of NLRP3 inflammatory vesicles in mice with viral myocarditis and inhibit the expression of the apoptotic factor caspase-3, thereby reducing cardiac cell death." (PMID 37405052, 2023). "In CVB3-induced viral myocarditis, IL-37 treatment obviously weakened the upregulation of NLRP3 inflammasomes (NLRP3, ASC, and caspase-1), and the activation of NLRP3 inflammasomes as evidenced by decreased inflammatory mediators (IL-1β and IL-18)." (PMID 36418383, 2022). "In the current study, we found that NLRP3 inflammasome was highly expressed in viral myocarditis with increased levels of IL-18 and IL-1β." (PMID 36418383, 2022). "In summary, our findings suggest the important role of calpain in the regulation of the NLRP3 inflammasome during the development of viral myocarditis." (PMID 35997820, 2022). "In viral myocarditis, myocardial cell pyroptosis is an important factor leading to the continuous decline of heart function and the activation of NLRP3 inflammasome is an important step leading to pyrolysis." (PMID 36418383, 2022). "In our study, we demonstrated that activated calpain in viral myocarditis promoted the activation of the NLRP3 inflammasome and then exacerbated viral myocarditis; therefore, inhibiting NLRP3 inflammasome activation may be beneficial in viral myocarditis." (PMID 35997820, 2022). "Moreover, the previous studies have shown that CVB3-induced myocardial NLRP3 contributed to the development of viral myocarditis." (PMID 35997820, 2022). "However, in viral myocarditis, the effects of IL-37 on NLRP3, pyrolysis, IL-1R8, etc. remain unclear." (PMID 36418383, 2022). "However, the precise mechanisms of regulation of NLRP3 inflammasome in the development of viral myocarditis remain largely unknown." (PMID 35997820, 2022). "Therefore, we speculated that IL-37 can improve viral myocarditis by inhibiting the activation of NLRP3 inflammasome-mediated pyroptosis." (PMID 36418383, 2022). "In the early stage of viral myocarditis, macrophages infiltrate the environment, and CVB3 capsid proteins have been shown to trigger the NLRP3 inflammasome, indicating a contributing role of macrophages to the pathogenesis of viral myocarditis." (PMID 40284705, 2025). "All of the miRs enriched in PEV had reported roles in the literature that inhibited specific pathways known to be involved in the pathogenesis of viral myocarditis including reducing viral replication, TLR4 signaling, inflammasome/NLRP3, and IL-1β." (PMID 39835120, 2024). "In the present study, we could demonstrate that MSC mediate an effective systemic immunoregulation in viral myocarditis via reduction of NOD2 expression and abrogation of NLRP3 inflammasome activation in macrophages (F4/80), NK cells (CD49b) and DCs (CD11c)." (PMID 29434214, 2018).
viral myocarditis (continued). "However, in the treatment of viral myocarditis, direct or indirect inhibition of NLRP3 inflammasome components or related pathways has not been reported." (PMID 34093086, 2021). "The functional characteristics of NLRP3 in the pathogenesis of coxsackievirus B3- (CVB3-) induced viral myocarditis (VMC) have not been fully elucidated, and the targeted therapeutic effect of NLRP3 or its related pathway in VMC has not been reported." (PMID 34093086, 2021).
abdominal aortic aneurysm (13 papers, 2015 to 2026). Enlargement and ballooning of the vessel that supplies arterial blood to the abdomen, pelvis and legs. "The nacht domain, leucine-rich repeat, and pyrin domain-containing protein 3 (NLRP3) inflammasome is upregulated in human abdominal aortic aneurysm (AAA), but its pathogenic role is unclear." (PMID 36262119, 2022). "NLRP3 knockdown and antagonism of inflammatory cytokines have been effective in preventing the occurrence of abdominal aortic aneurysms in animal models." (PMID 37752552, 2023). "Moreover, a study has reported that inhibition of the mouse inflammatory pathway (NLRP3–caspase-1–GSDMD) can effectively reduce abdominal aortic aneurysm occurrence in mice." (PMID 37752552, 2023). "This conclusion aligns with previous studies, such as the inhibition of NLRP3 inflammasome, coincident with the downregulation of MMP2 expression in the lesion site of abdominal aortic aneurysm (AAA), and the prevention of elastin degradation." (PMID 38992615, 2024).
acute myeloid leukemia (13 papers, 2018 to 2025). Acute myeloid leukemia (AML) is a group of neoplasms arising from precursor cells committed to the myeloid cell-line differentiation. "However, the role of NLRP3 inflammasome in acute myeloid leukemia (AML) remains unclear." (PMID 34211462, 2021). "Lastly, the NLRP3 inflammasome contributes to the development of myeloid leukemias, where its activation has been found in chronic myelomonocytic leukemia (CMML), juvenile myelomonocytic leukemia (JMML), and acute myeloid leukemia (AML) patients harboring KRAS mutations." (PMID 35740272, 2022).